MTOR (mechanistic target of rapamycin kinase)
Diseases named in the same sentence as MTOR in open-access papers (continued):
Sharing a sentence is not in itself a finding about the gene and the disease.
bone sarcoma (7 papers, 2011 to 2023). A sarcoma that arises from the bone. "Previously, maintenance therapy with an mTOR inhibitor, ridaforolimus in adults with soft tissue or bone sarcoma was explored, although with minimal clinical benefit." (PMID 37724607, 2023). "Trials with single agent mTOR inhibition have provided clinical benefit at 16 weeks on the order of 13 to 27% in metastatic soft tissue and bone sarcomas." (PMID 27295141, 2016). "AKT/mTOR inhibitors are currently in phase I/II clinical trials for adult malignancies and drugs such as everolimus, alpelisib, and MK-2206 have also been tested against bone sarcomas with variable results." (PMID 34903601, 2022). "Thus, we tested a potent drug for skeletal sarcoma treatment, which inhibits the pro-oncogenic protein mTOR, called RAD-001 (Everolimus, Novartis)." (PMID 21437224, 2011).
breast adenocarcinoma (7 papers, 2020 to 2024). "Authors also found that oleocanthal (at a concentration of 10 μM) downregulated the expression of phosphorylated mTOR in the metastatic breast adenocarcinoma cell line MDA-MB-231." (PMID 38139152, 2023). "This study conducted an in vitro library screening to suppress the self-renewal ability of spheres derived from canine mammary adenocarcinoma CTBp and CNMp lines and extracted molecular-targeted inhibitors, such as mTOR, hedgehog, and proteasome." (PMID 36816969, 2023). "This study focused on the mTOR signaling pathway evaluated by western blotting and the in vitro and in vivo antitumor effects of adherent cells and sphere-forming cells derived from canine mammary adenocarcinoma lines." (PMID 36816969, 2023). "In this study, the microarray results suggested that the effect of SCA on breast adenocarcinoma cells might be dependent on the regulation of the PI3K–Akt–mTOR signaling pathway." (PMID 36408240, 2022). "Western blotting was performed to confirm the expression of mTOR signal-related proteins, such as mTOR and 4E-BP1 in adherent and sphere-forming cells from canine mammary adenocarcinoma lines." (PMID 36816969, 2023). "Curcumin triggered down-regulation on PKM2 via mTOR-HIF-1α inhibition in H1299 non–small cell lung cancer cells, MCF7 breast adenocarcinoma cells, HeLa cervical adenocarcinoma cells, and PC-3 prostate adenocarcinoma cells, reversing the Warburg effect." (PMID 35890106, 2022). "Similarly, in MCF7 breast adenocarcinoma cells, licochalcone A inhibited PI3K/Akt/mTOR activation, promoting autophagy and apoptosis." (PMID 35890106, 2022). "Furthermore, the cytotoxic effects against human breast adenocarcinoma cells (MCF-7) and its ability to affect mammalian (or mechanistic) target of rapamycin (mTOR) and nuclear factor kappa-light-chain-enhancer of activated B cells (NF-κB) signaling were evaluated." (PMID 32405891, 2020).
cervical adenocarcinoma (7 papers, 2010 to 2025). An adenocarcinoma arising from the cervical epithelium. "Overall, p-mTOR expression was reported to be an independent and predictive indicator of cervical adenocarcinoma." (PMID 36428613, 2022). "The same authors also investigated the expression of phosphorylated mTOR was independent and was a significant prognostic marker in cervical adenocarcinoma." (PMID 35477450, 2022). "The investigators also explored activated AKT (p-AKT) and mTOR (p-mTOR) expression among patients diagnosed with cervical adenocarcinoma." (PMID 36428613, 2022). "The findings demonstrated in 50% and 53% of cervical adenocarcinomas, respectively, that p-AKT and p-mTOR were determined." (PMID 36428613, 2022).
cervical squamous cell carcinoma (7 papers, 2014 to 2025). A squamous cell carcinoma arising from the cervical epithelium. "PI3K/Akt/mTOR pathway is crucial in some cancers, but its relation with tumor-infiltrating immune cells in cervical squamous cell carcinoma and endocervical adenocarcinoma (CESC) is unanalyzed." (PMID 41366959, 2025). "The expression of mTOR in invasive squamous cell carcinomas of the cervix increases progressively according to the grade of malignancy." (PMID 36428613, 2022). "Second, matched therapy targeting the activated PI3K/AKT/mTOR pathway in patients with metastatic or recurrent squamous cell carcinoma of the cervix led to a favorably higher rate of SD ≥ 6 months/CR/PR as well as significantly longer PFS and OS than non-matched therapy." (PMID 25426553, 2014). "In addition, previous studies have found that the levels of mTOR and pmTOR expression were elevated in extrahepatic cholangiocarcinoma and high-grade cervical squamous cell carcinoma, respectively, when compared with normal cervical epithelium." (PMID 25120661, 2014). "However, contrary to our finding, it was previously reported that in cervical squamous cell carcinoma cells, DEPTOR silencing activated p38 MAPK in an mTOR-independent manner, promoting cell apoptosis." (PMID 29670094, 2018).
CNS lymphoma (7 papers, 2018 to 2024). "Aberrant activation ofPI3K/AKT/mTOR signaling pathway has been demonstrated in primary central nervous system lymphoma PCNSL." (PMID 39054516, 2024). "More interestingly, mTOR-independent phosphorylation of RPS6 was frequently identified in primary central nervous system lymphoma (PCNSL) and DLBCL." (PMID 35008473, 2021). "Various clinical trials have investigated the effects of small molecules targeting these pathways and immune checkpoint inhibitors, such as immunomodulatory imide drugs, PI3K/AKT/mTOR inhibitors, and immune checkpoint inhibitors, for the treatment of CNS lymphoma." (PMID 37929016, 2023). "Numerous clinical trials have investigated the therapeutic potential of combining BTK inhibitors with other drugs for CNS lymphoma treatment, including chemotherapy agents, immune checkpoint inhibitors, PI3K/AKT/mTOR inhibitors, immunomodulatory imide drugs, and various multi‐agent combinations." (PMID 37929016, 2023). "A recent metabolomic profiling demonstrated that glycolysis was excessive via PI3K/AKT/mTOR and RAS/MAPK Signaling in methotrexate-resistant PCNSL-derived cells, which is valuable to understanding targeted therapies with selective anticancer drugs in recurrent CNS lymphoma." (PMID 38557926, 2024).
Cushing syndrome (7 papers, 2022 to 2024). Cushing's syndrome (CS) encompasses a group of hormonal disorders caused by prolonged and high exposure levels to glucocorticoids that can be of either endogenous (adrenal cortex production) or exogenous (iatrogenic) origin. "Recently, it has been reported that Cushing’s syndrome patients with increased cortisol secretion exhibit reduced mTOR function while inhibition of the mTOR pathway on the adrenal glands can reduce cortisol secretion." (PMID 36297314, 2022).
dysplasia (7 papers, 2013 to 2023). A usually neoplastic transformation of the cell, associated with altered architectural tissue patterns. "Hyperactive mTOR signaling in the brain is associated with characteristic lesions, such as focal cortical dysplasia, seizures, macrocephaly and benign brain tumors." (PMID 37298625, 2023).
epileptic encephalopathies (7 papers, 2014 to 2025). "Loss of mTOR negative regulators and subsequent over-activation of mTOR signaling are major causes underlying epileptic encephalopathy." (PMID 34309811, 2021). "Loss of mTOR-negative regulators and over-activation of the mTOR signaling pathway are major causes underlying the occurrence of cortical malformations and epileptic encephalopathy." (PMID 34309811, 2021).
Fabry disease (7 papers, 2015 to 2023). Fabry disease (FD) is a progressive, inherited, multisystemic lysosomal storage disease characterized by specific neurological, cutaneous, renal, cardiovascular, cochleo-vestibular and cerebrovascular manifestations. "Moreover, autophagy dysregulation has also been implicated in podocyte damage in Fabry disease due to the inhibition of mammalian target of rapamycin (mTOR), a key enzyme that regulates autophagy." (PMID 26064721, 2015). "In conclusion, there is mTOR pathway dysfunction in sphingolipidoses, as observed in both PBMCs derived from patients with Gaucher and Fabry diseases, which leads to impaired autophagy and mitochondrial stress." (PMID 30633777, 2019). "In support of this idea, studies have demonstrated mTOR signal dysregulation in various LSD models such as Fabry disease, Pompe disease and mucopolysaccharidoses." (PMID 31519738, 2019). "Impaired mTOR reactivation and defective lysosome reformation were observed in fibroblasts from patients with Scheie syndrome, Fabry disease, and Aspartylglucosaminuria." (PMID 28130275, 2017). "In Anderson–Fabry disease, the accumulation of sphingolipid substrates in lysosomes inhibits autophagosome–lysosome fusion and disrupts the mTOR activation/inactivation cycle, interfering with the mTOR-mediated control of mitochondrial metabolism." (PMID 36285443, 2022). "Reduced basal mTOR activity has also been observed in diverse models of lysosomal diseases including Neuronal Ceroid Lipofuscinosis type 3 lymphoblastoid cells, in NPC1- and NPC2-knockdown endothelial cells, in a Drosophila model of mucolipidosis IV, and a human podocyte model of Fabry disease." (PMID 34831346, 2021).
fungal infections (7 papers, 2011 to 2025). "Studies have shown that mTOR plays a fundamental role in the protection of epithelial cells during fungal infections as well as in the induction of monocytes via trained immunity." (PMID 28797245, 2017). "It has been reported that the fungal cell wall component β-glucan can prime monocytes/macrophages to mount an enhanced innate response against fungal infection by activating the mTOR pathway." (PMID 26439699, 2015).
ganglioglioma (7 papers, 2016 to 2025). A well differentiated, slow growing neuroepithelial neoplasm composed of neoplastic, mature ganglion cells and neoplastic glial cells. "We found evidence of neoplastic cell dual perturbations to BRAF/MEK and PI3K/AKT/mTOR pathways and identified ganglioglioma gene regulatory networks (resembling those present during neuroectoderm neural development) and associated immune cell states." (PMID 36966348, 2023). "A mouse model of BRAF-V600E neuroectodermal tumors required a second hit with increased AKT/mTOR signaling to produce ganglioglioma-like tumors." (PMID 36966348, 2023).
kidney injury (7 papers, 2012 to 2025). Trauma to the kidney. "In the present study, the mTOR agonist MHY1485 was employed to investigate the regulatory mechanisms of autophagy in Cd-induced kidney injury." (PMID 40141229, 2025). "Above all, these results indicate that DEX can enhance autophagy through the AMPK/mTOR pathway in acute kidney injury induced by LPS." (PMID 32670056, 2020). "The results of this study indicate that activation of mTOR exerts an inhibitory effect on autophagy, which exacerbates Cd-induced renal cell pyroptosis, suggesting a protective role for autophagy in Cd-induced kidney injury." (PMID 40141229, 2025). "Importantly, in both in vivo and in vitro experiments, rapamycin, an mTOR inhibitor, downregulated the expression of pyroptosis-related proteins, thereby significantly improving Cd-induced kidney injury." (PMID 40141229, 2025). "Mammalian target of rapamycin (mTOR) plays a vital role in regulating mRNA translation, metabolism, and protein turnover, and mTOR complex 1 (mTORC1) signaling has been widely reported to be involved in acute hepatic I/R, cisplatin induced-acute kidney injury and postnatal brain development." (PMID 36494334, 2022). "Therefore, the balance of mTOR signaling activation could be a key to control the outcome of kidney injuries." (PMID 22470459, 2012). "In this study, we observed the different expression pattern of mTOR signaling between reversible IRI and progressive fibrotic models, which indicated the induction of mTOR activation after kidney injury might therefore serve a dual purpose." (PMID 22470459, 2012).
leukopenia (7 papers, 2013 to 2024). "The cell lines derived from the 8-year-old patient and his mother affected by mild MF and leukopenia, respectively, show an mTOR hypophosphorylation, an altered dynamicity in the mitochondrial network, and an aerobic metabolism derangement." (PMID 38396760, 2024).
liver cirrhosis (7 papers, 2014 to 2024). "This, in turn, affects a range of signal transduction-related proteins like CREB, LSD1, PPARγ, mTOR, and PRAS40, all of which are associated with liver cirrhosis." (PMID 38429802, 2024). "The authors confirmed that a clinically meaningful inhibition of the mTOR pathway in patients with liver cirrhosis cannot be achieved by using everolimus because of its toxicity." (PMID 32070029, 2020). "In conclusion, we have demonstrated naringin in GSG suppressed activation of HSCs for anti‐fibrosis effect by inhibition of mTOR, indicating a potential therapeutic application for liver cirrhosis." (PMID 27687505, 2017).
malaria (7 papers, 2015 to 2025). Malaria is a serious and sometimes fatal disease caused by a parasite that commonly infects a certain type of mosquito which feeds on humans. "Consistent with this, Ag-expTh1 cells exhibited significantly higher and sustained mTOR activity than effector T-bet– (non-Th1) Ag-expT cells throughout the course of malaria." (PMID 32817333, 2020). "This identifies placental mTOR as a potentially valuable target for interventions aimed at improving birthweight in malaria in pregnancy." (PMID 28049467, 2017). "Our findings identify placental mTOR as a potentially valuable target for interventions aimed at improving birthweight in malaria in pregnancy." (PMID 28049467, 2017). "Our findings open novel avenues of research to develop interventions targeting placental mTOR signaling to improve birthweight and neonatal health in malaria-exposed populations." (PMID 28049467, 2017). "Cytokines such as IL-1β have been shown to inhibit mTOR activity and similar cytokine profiles have been reported in malaria-infected pregnant women." (PMID 28049467, 2017). "Specifically, we demonstrate that mTOR signaling is inhibited in placental malaria-associated intervillositis and in cultured PHT cells exposed to malaria-infected conditioned media." (PMID 28049467, 2017). "Further research on the role of mTOR is necessary in placental malaria animal model, such as the baboon, where Plasmodium knowlesi have been shown to sequester to the placenta." (PMID 26587536, 2015). "mTOR inhibition triggered by the inflammatory response to malaria could be responsible for the increased autophagosome formation in placental malaria with intervillositis, as evidenced by the higher LC3-II:LC3-I ratio in these placentas." (PMID 29125872, 2017). "While malaria parasites have lost most of the TORC components through genomic reduction, including mTOR, mLST8, Raptor, and Rictor, the parasites are able to control protein synthesis via various mechanisms of translational regulation." (PMID 35889137, 2022). "We determined the link between intervillositis, mTOR signaling activity, and amino acid uptake in tissue biopsies from both uninfected placentas and malaria-infected placentas with and without intervillositis, and in an in vitro model using primary human trophoblast (PHT) cells." (PMID 28049467, 2017).
mesenchymal neoplasms (7 papers, 2012 to 2026). "Adding that only 50% of human mesenchymal tumors, and 31% of Tsc2+/− mouse renal tumors exhibit altered mTOR pathway activation, supports the existence of tumorigenic mTOR-independent mechanisms causing LAM pathogenesis." (PMID 32365712, 2020). "These tumors represent a family of mesenchymal neoplasms, mechanistically linked through activation of the mTOR signaling pathway." (PMID 22943457, 2012). "Perivascular epithelioid cell tumors (PEComa) represent a family of rare mesenchymal tumors resultant from deregulation in mTOR pathway activity." (PMID 34442003, 2021). "mTOR signalling positively correlated with TAM‐MG enrichment but not with TAM‐BMDM at transcriptomic level in the TCGA samples, a finding that was most prevalent in mesenchymal tumours, and thus, we applied the assay to hGIC/iMGL derived from GBM classified as belonging to the mesenchymal subtype." (PMID 32567735, 2020).
migraine (7 papers, 2020 to 2026). "Our analyses found that the decline of erectile function in a rat model of migraine was associated with the PI3K/Akt/mTOR signaling pathway." (PMID 33997039, 2021). "The decline of erectile function in a rat model of migraine was associated with the PI3K/Akt/mTOR signaling pathway." (PMID 33997039, 2021). "Furthermore, the levels of essential neurotransmitters in the brain, such as serotonin, were significantly reduced, thus proving that the PI3K/Akt/mTOR signaling pathway is one of the dominant mechanisms underlying migraine." (PMID 33997039, 2021). "The analysis of GWAS statistics and perturbagen data identified the mammalian target of rapamycin (mTOR) as a potential target for migraine." (PMID 41355896, 2025). "Down-regulation of mGluR5 in a rat model of migraine activates autophagy by inhibiting the mTOR pathway and reduces the expression of central sensitization-related proteins CGRP and SP." (PMID 35694442, 2022). "In this study, we found that the expression levels of PI3K, p-AKT, and p-mTOR proteins and PI3K, Akt, and mTOR mRNAs in the penile tissue of rats that experienced migraine were significantly reduced." (PMID 33997039, 2021). "Therefore, we believe that the decline of erectile function in rats experiencing migraine is closely related to the PI3K/Akt/mTOR signaling pathway." (PMID 33997039, 2021). "In the present study, we used bioinformatic technology to demonstrate that the PI3K/Akt/mTOR signaling pathway may represent a potential mechanism for the effects of migraine on erectile function." (PMID 33997039, 2021). "In the present study, we mined a range of biological data and discovered that the association between migraine and ED might be related to the PI3K/AKT/mTOR pathway." (PMID 33997039, 2021). "However, whether migraine can affect erectile function via the PI3K/Akt/mTOR pathway remains unclear." (PMID 33997039, 2021). "We hypothesized that S. gallolyticus may exacerbate migraine pain by initiating MAPK and PI3K/Akt/mTOR cascades." (PMID 41454664, 2026). "In the context of migraine, the activation of the phosphoinositide 3-kinase (PI3K)/protein kinase B (PKB/Akt) signaling pathway exerts a direct influence on the mammalian target of rapamycin (mTOR), leading to a reduction in autophagy levels." (PMID 40027467, 2025). "Furthermore, we found that migraine can inhibit the expression of key proteins and mRNAs in the PI3K/Akt/mTOR pathway, and these factors together lead to the decline of erectile function." (PMID 33997039, 2021).
myelofibrosis (7 papers, 2013 to 2022). A partial or complete replacement of the bone marrow stroma by fibrous tissue. "Furthermore, VEGF significantly increased the expression of HIF-1α and eNOS genes, the latter inversely regulated by PI3K and mTOR signaling in the MNC of primary myelofibrosis (PMF)." (PMID 34206393, 2021). "Everolimus, an mTOR inhibitor, was investigated in a study of 30 patients with myelofibrosis." (PMID 31244289, 2019). "The levels of CIP2A were found increased in cells harboring the JAK2V617F mutation, and we provide evidence of a correlation between clinical responses and the extent of CIP2A downregulation in myelofibrosis patients receiving the mTOR inhibitor RAD001 in a phase II clinical trial." (PMID 29228564, 2017). "Lastly, as discussed in this review, PI3K/mTOR/AKT inhibitors and telomerase inhibitors have also shown much potential, and further studies are warranted to explore this treatment option for primary myelofibrosis." (PMID 31244289, 2019).